CTNNAL1 (catenin alpha like 1)
Description:
May modulate the Rho pathway signaling by providing a scaffold for the Lbc Rho guanine nucleotide exchange factor (ARHGEF1).
Synonyms: ACRP; CLLP; alpha-CATU
Tractability: Antibody: UniProt places it where antibodies can reach, with high confidence; its Gene Ontology location is reachable by antibodies, with medium confidence. PROTAC: ubiquitination databases record sites on it; its protein half-life has been measured.
Gene: Protein-coding gene on chromosome 9 (108,942,569 to 109,013,645, reverse strand). Ensembl gene ENSG00000119326.
Subcellular location: Cytoplasm, cytoskeleton; Cell membrane
Gene Ontology:
Molecular function: protein binding; actin filament binding; cadherin binding
Biological process: Rho protein signal transduction; cell adhesion
Cellular component: cytosol; cytoplasm; cytoskeleton; plasma membrane
Genetic constraint (gnomAD): Loss-of-function variants: 53 observed, 74.22 expected, observed/expected ratio (o/e) 0.71, 90% interval 0.57 to 0.9. The upper end of that interval is the gene's LOEUF score, 0.9, which puts it in group 3 of 6, group 1 being the genes least tolerant of losing a copy. Missense variants: 712 observed, 736.44 expected, observed/expected ratio (o/e) 0.97, 90% interval 0.91 to 1.03. Synonymous variants: 251 observed, 261.57 expected, observed/expected ratio (o/e) 0.96, 90% interval 0.87 to 1.07.
Homologues: Orthologues: chimpanzee CTNNAL1 (99% identical), macaque CTNNAL1 (99% identical), dog CTNNAL1 (93% identical), rabbit CTNNAL1 (92% identical), mouse Ctnnal1 (87% identical), rat Ctnnal1 (87% identical), guinea pig CTNNAL1 (87% identical), tropical clawed frog ctnnal1 (71% identical), zebrafish ctnnal1 (62% identical), Caenorhabditis elegans ctn-1 (40% identical), Drosophila melanogaster alpha-Catr (30% identical). Paralogues in human: CTNNA2 (25% identical), CTNNA1 (23% identical), CTNNA3 (21% identical), VCL (18% identical).
Diseases named in the same sentence as CTNNAL1 in open-access papers:
CTNNAL1 is named in the same sentence as 21 diseases in open-access papers, as found by Europe PMC text mining. Sharing a sentence is not in itself a finding about the gene and the disease. The quoted sentences say what the papers report.
asthma (5 papers, 2012 to 2024). "In our previous work, we have shown that the airway epithelial defect in asthma is closely associated with abnormal expression of epithelial adhesion molecules such as CTNNAL-1, ICAM-1 and integrin-β4 50-52." (PMID 35173551, 2022). "Some studies have found that the expression of the CTNNAL1 gene (adhesion molecule catenin alpha-like 1) is reduced in the epithelial cells of the lower respiratory tract in patients suffering from asthma." (PMID 40007819, 2024). "Previously, we reported that catenin alpha-like 1 (CTNNAL1) is downregulated in an asthma animal model and upregulated at the edge of human bronchial epithelial cells (HBECs) after ozone stress." (PMID 38602002, 2024). "Silencing the Ctnnal1 gene using RNA interference led to a 60% reduction in gene expression and, consequently, an exacerbation of asthma symptoms after allergen exposure: mucus hypersecretion, airway inflammation, and increased goblet cell hyperplasia." (PMID 40007819, 2024). "In all, our study demonstrates that CTNNAL1 plays an important role in HDM‐induced asthma, mediating mucus secretion through the YAP‐ROCK2 pathway." (PMID 35092120, 2022). "Our previous study indicated that adhesion molecule catenin alpha‐like 1(CTNNAL1) is downregulated in airway epithelial cells of asthma patients and asthma animal model but little is known about how the CTNNAL1 affects asthma pathogenesis." (PMID 35092120, 2022). "Our previous study showed that the adhesion molecule catenin alpha‐like‐1 (CTNNAL1) was downregulated in asthma patients and in ovalbumin‐stressed asthma mouse model." (PMID 35092120, 2022). "Our previous study indicated catenin alpha-like 1 (CTNNAL1), an alpha-catenin-related protein, was downregulated in asthma patients and animal model." (PMID 22359570, 2012). "In the previous study, we found that CTNNAL1 mRNA decreased in the lung of OVA-sensitized asthma animal model." (PMID 22359570, 2012). "There was a negative correlation between the pulmonary resistance (RL) in asthma mice and the levels of CTNNAL1 mRNA in the 8-day time course after the OVA challenge." (PMID 22359570, 2012). "Taken together, our results suggest that CTNNAL1 is involved in maintaining the integrity of the airway epithelium and down regulation of CTNNAL1 expression might contribute to epithelial dysfunction and asthma development." (PMID 22359570, 2012).
melanoma (5 papers, 2014 to 2023). A malignant, usually aggressive tumor composed of atypical, neoplastic melanocytes. "In breast cancer, CTNNAL1 has been reported as a cancer suppressor gene, and in melanoma and lung cancer, it has been reported as a cancer driver gene." (PMID 37239133, 2023). "On the other hand, Ctnnal1 played a positive role in EMT and cell migration in melanoma cells." (PMID 33748116, 2021).
breast carcinoma (4 papers, 2020 to 2023). "Numb-KD1, Numb-KD2, and Ctnnal1-KD2 cells exhibited faster wound closure than that in negative control (NC) cells, indicating that down-regulated Numb and Ctnnal1 enhanced breast cancer cell migration." (PMID 33748116, 2021). "In our study, knockdown of Ctnnal1 in 4T1 cells enhanced breast cancer cell migration, which was consistent with the effect of IFT20 depletion." (PMID 33748116, 2021). "In keeping, we showed that ZNF750 negatively regulates cell migration and invasion in breast cancer cells; in particular, ZNF750 binds and recruits KDM1A and HDAC1 on the LAMB3 and CTNNAL1 promoters." (PMID 33298895, 2020). "The expression of CTNNAL1 and LAMB3 inversely correlated with ZNF750 expression in breast cancer." (PMID 35879327, 2022). "Using proximity-dependent biotin identification (BioID) and Strep-Tactin pulldown assays, IFT20 was found to participate in the vesicular transport of Numb and Ctnnal1 from the trans-Golgi/TGN to the plasma membrane; moreover, both IFT20 interactors inhibited breast cancer cell migration." (PMID 33748116, 2021). "In fact, we would like to speculate that besides repressing LAMB3 and CTNNAL1 expression, ZNF750 might also inhibit migration and invasion in breast cancer by repressing the expression of RAC1." (PMID 33298895, 2020). "They showed that zinc-finger protein 750 (ZNF750) is a negative regulator of the migration, and invasion of breast cancer cells by repressing a prometastatic transcriptional program, which includes genes involved in focal adhesion and extracellular matrix interactions, such as LAMB3 and CTNNAL1." (PMID 35879327, 2022).
lung carcinoma (4 papers, 2015 to 2023). "Previous studies have shown that CTNNAL1 is overexpressed in various types of cancer, including lung cancer, and is associated with tumor progression and a poor prognosis." (PMID 37239133, 2023). "The same results were obtained in GBM cells and lung cancer cells, suggesting that CTNNAL1 plays the same role in both cancer types." (PMID 37239133, 2023). "In this study, it is shown that CTNNAL1 regulates cancer stem cells (CSCs) in lung cancer and glioblastoma and modulates their migration and invasion abilities." (PMID 37239133, 2023). "In the salmon module, the hub Scube3 is a TGF-β receptor ligand that induces EMT in lung cancer, whereas Ctnnal1 (catenin alpha-like 1) inhibits EMT in bronchial epithelial cells by reducing TGF-β levels." (PMID 32831131, 2020). "This study suggests that CTNNAL1 may be a potential therapeutic target for the treatment of lung cancer and GBM." (PMID 37239133, 2023). "The secretion of CCL2 was regulated by CTNNAL1 in lung cancer cells." (PMID 37239133, 2023). "We identified CTNNAL1 as a gene that is commonly overexpressed in ALDH1+ lung cancer cells and CD133+ GBM cells; however, its function in GBM cells is unknown." (PMID 37239133, 2023). "Silencing the CTNNAL1 gene reduces CSC properties and enhances sensitivity to irradiation in lung cancer." (PMID 37239133, 2023).
Hirschsprung disease (3 papers, 2015 to 2025). Hirschsprung disease (HSCR) is a congenital intestinal motility disorder that is characterized by signs of intestinal obstruction due to the presence of an aganglionic segment of variable extent in the terminal part of the colon. "Taken together, our present data show that genetic variants and haplotypes in RET, ARHGEF3 and CTNNAL1 confer an altered risk to Hirschsprung disease in the Han Chinese population." (PMID 32139661, 2020). "Our current work presented strong associations of ARHGEF3 and CTNNAL1 with Hirschsprung disease." (PMID 32139661, 2020). "Of these genes, LAMA4, ZEB2, CTNNAL1, ITGA6 and ITIH5 have previously been associated with Hirschsprung’s disease and ZEB2 was shown to genetically interact with SOX10." (PMID 39982575, 2025). "Furthermore, supporting the hypothesis that Ctnnal1 is a candidate gene for Hirschsprung disease, here we show that the gene is expressed in the enteric nervous system, which is the primary site of disease manifestation." (PMID 26398943, 2015).
COVID-19 (1 paper, 2023). A disease caused by infection with severe acute respiratory syndrome coronavirus 2. "Several of these genes (PELI1, MAP3K8, LAMA3, EMP2, CTNNAL1, CAV1, LRRK2, SFRP4) may also be involved in lung fibrosis, a severe complication of COVID-19." (PMID 37561814, 2023).
diabetes (1 paper, 2025). "Furthermore, a number of genes in this set (Peak1, Astn2, Bcar1, Ctnnal1, Ppfibp2) is associated with significant diabetes-related risk loci." (PMID 40667025, 2025).
enteritis (1 paper, 2021). Inflammation of the small intestine. "The relative abundance of invasive pathogenic bacteria Spirochaetes, which causes enteritis in cattle, was associated with high IgG1 level and was also associated with one SNP located in the CTNNAL1 gene, catenin alpha-like 1 protein, which affects the NF-kB and MAPK pathways." (PMID 33649551, 2021).
glioma (1 paper, 2023). A benign or malignant brain and spinal cord tumor that arises from glial cells (astrocytes, oligodendrocytes, ependymal cells). "CTNNAL1 may be a novel target for treating lung CSCs and glioma stem cells and may be used as a marker of malignancy." (PMID 37239133, 2023).
lung adenocarcinoma (1 paper, 2022). A carcinoma that arises from the lung and is characterized by the presence of malignant glandular epithelial cells. "Taken together, our results suggest that the 3-gene signature of CTNNAL1 plus ILK plus KLF5 can be used to predict the outcome of patients with lung adenocarcinoma." (PMID 35154481, 2022). "In the clinic, we compared the expression levels between CTNNAL1 and stemness-associated gene sets obtained from the TCGA-LUAD lung adenocarcinoma dataset." (PMID 35154481, 2022). "Importantly, we identify a CTNNAL1/ILK/KLF5 three-gene signature for predicting poor overall survival in patients with lung adenocarcinoma." (PMID 35154481, 2022).
pancreatic cancer (1 paper, 2012). "Catenin alpha-like-1(CTNNAL1) was first characterized as a 2.45-kb transcript that was down-regulated in human pancreatic cancer cells." (PMID 22359570, 2012).
rheumatoid arthritis (1 paper, 2019). A chronic, systemic autoimmune disorder characterized by inflammation in the synovial membranes and articular surfaces. "Another gene in the same locus as CTNNAL1 is KLF4, which has been found to interact with TNF-α in rheumatoid arthritis." (PMID 31031798, 2019).
cancer (2 papers, 2023 to 2024). A tumor composed of atypical neoplastic, often pleomorphic cells that invade other tissues. "In addition, we observed that CTNNAL1 regulates the ability of cells to migrate and invade, a key feature of the epithelial to mesenchymal transition phenomenon associated with cancer metastasis." (PMID 37239133, 2023). "Alterations in the expression or function of CTNNAL1 have been reported to contribute to the development and progression of various types of cancer." (PMID 37239133, 2023). "CTNNAL1 encodes a protein that is thought to facilitate actin filament and cadherin binding activity and is known to be highly expressed in normal pancreas but is down regulated in the ASPC-1 cancer cell line upon sodium butyrate treatment." (PMID 39112965, 2024). "Therefore, the regulation of CCL2 by CTNNAL1 is thought to be related to immune cells as well as the malignancy of cancer cells." (PMID 37239133, 2023).
infection (2 papers, 2014 to 2024). The state of being infected such as from the introduction of a foreign agent such as serum, vaccine, antigenic substance or organism. "Ctnnal1 is also important in the cell adhesion process and for capturing bacterial molecules to eliminate infection." (PMID 25283706, 2014).
tumor (2 papers, 2022 to 2023). "We found that the expression of CTNNAL1 was high in the tumor sphere samples but was decreased in the sphere-derived adherent cells generated by continual passage under serum-containing conditions." (PMID 35154481, 2022).
CTNNAL1 also shares sentences with these, for which no sentence is quoted: adenocarcinoma (1 paper); glioblastoma (1); Infertility (1); lung fibrosis (1); psoriasis (1); psoriatic arthritis (1).